IL1B (interleukin 1 beta)
Diseases named in the same sentence as IL1B in open-access papers (continued):
Sharing a sentence is not in itself a finding about the gene and the disease.
cardiovascular disease (continued). "Therefore, SDG reduces IL-1β, TNF-α, and IL-6 expression, which indirectly reduce the damage of endothelial cells and the risk of cardiovascular disease." (PMID 32684834, 2020). "IL-1β is a major proinflammatory cytokine in the pathogenesis of cardiovascular diseases." (PMID 31534437, 2019). "Although the relationship between IL-1β and cardiovascular disease has been extensively studied, IL-1β expression and its related mechanism in LPS-induced human aortic smooth muscle cells (HASMCs) and in inflammatory vascular walls have not been studied in detail." (PMID 24723958, 2014). "This may be clinically important, not only for its impact on acute Gouty Arthritis and the risk of recurrent flares, but also because of the possible role of elevated CRP and SAA levels and IL-1β in the development of cardiovascular disease." (PMID 21439048, 2011). "Despite the reduced number of participants in the cardiovascular disease group (only 4 participants), all those inflammatory cytokines were detected in this disease group, with statistically significant levels (compared to control group) being observed mainly for IL-1β and IL-6." (PMID 39328992, 2024). "Therefore, pharmacological inhibition of IL-1β could be a promising approach for the treatment of cardiovascular diseases." (PMID 35804014, 2022). "In addition, the higher titers of MMP in the amlodipine arm may be related to harmful effects on endothelial cells because MMP contains interleukin 1-beta (IL-1β), a cytokine that activates the inflammatory cascade related to cardiovascular disease." (PMID 31721907, 2019). "Canakinumab targets IL-1β–dependent inflammation, thereby potentially preserving/improving pancreatic β-cell function and inhibiting progression to atherothrombosis in the coronary arteries of T2DM patients who are at a high risk of developing cardiovascular disease." (PMID 24884602, 2014). "Hyper-inflammatory IL-1β enriched monocytes may be a major source of IL-6 production and systemic inflammation in HIV-infected adults, and may contribute to the risk for all-cause mortality and cardiovascular disease in treated HIV infection." (PMID 24086545, 2013). "IL-1β and MPO are known biomarkers of atherosclerotic inflammation and contribute to cardiovascular disease (CVD) progression." (PMID 40862746, 2025). "Interleukin‐1β (IL‐1β) antagonists such as anakinra have emerged as potential treatment options and have been shown to reduce NLR values in cardiovascular disease." (PMID 41098018, 2025). "Furthermore, we demonstrated a significant correlation between IL-1β levels, markers of endothelial injury, and impaired coronary microvascular function, providing novel mechanistic insights into the pathophysiology of cardiovascular disease in this vulnerable population." (PMID 41573504, 2025). "Similar to other infections (e.g. HIV, sepsis, pneumonia), TB-induced cardiovascular disease likely stems from proinflammatory cytokines (e.g. TNF, IL-6, Il1β) that impair endothelial function, resulting in plaque rupture, and vascular occlusion." (PMID 40475250, 2025). "In patients with cardiovascular disease, dietary PUFA levels were inversely correlated with inflammatory markers, including C-reactive protein (CRP) and interleukin 1β (IL1β)." (PMID 39664126, 2024). "This review focuses on the activation and regulation mechanism of inflammasomes, the role of inflammasomes in cardiovascular diseases, and the research progress of targeting NLRP3 inflammasome and IL-1β for related disease intervention." (PMID 35464402, 2022). "Studies have confirmed that the changes in the levels of SAH, IL-1β, Hcy, TNF-α, and BDNF in the human body are closely related to cardiovascular diseases." (PMID 35282820, 2022). "In particular, a chronic increase of plasma levels of pro-inflammatory cytokines such as interleukins IL-6, IL-1β, IL-17, and TNF-α is known to characterize cardiovascular diseases including IHD." (PMID 34112104, 2021).
cardiovascular disease (continued). "Studies have shown that main neuroactive cytokines involved in hypothalamic inflammatory mechanisms related to cardiovascular diseases are TNF-α, IL-6, IL1-α/IL-1β, and IL-10." (PMID 33967677, 2021). "Clinical trials have confirmed that IL-1β and its receptor antagonist could be used to treat a variety of cardiovascular diseases, and the widely used drug glyburide played a crucial role in the treatment of cardiovascular diseases through the inhibition of the NLRP3 inflammasome." (PMID 32377298, 2020). "IL-1β and IL-18, two key cytokines regulated by NLRP3 inflammasome activation, participate in endothelial inflammation and cardiovascular disease in humans." (PMID 32439949, 2020). "Upregulation of major cardiovascular disease related proinflammatory cytokines, TNF-α, IL-1β and IL-6, were inhibited with anti-LOX-1 receptor antibody treatment." (PMID 32182251, 2020). "Nevertheless, our work strongly suggests that clinical interventions via targeting IL-1β may be of limited value; the cholesterol control at the very early stage of atherosclerotic changes should be a more viable method for the prevention of cardiovascular diseases." (PMID 29896195, 2018). "IL-1β up-regulated HDAC9; HDACs (histone deacetylases) are involved in atherogenesis and HDAC-inhibitors are a potential therapeutic target for cardiovascular disease." (PMID 28323859, 2017). "Treatments that significantly modulated TNF‐α secretion were further explored for their effect on IL‐1β, as with TNF‐α, IL‐1β is a critical mediator in inflammation where blockade inhibits the progression of cardiovascular disease." (PMID 25801720, 2015). "In addition to modifying IL-1α, IL-1β, IL-6, TNF-α, and IL-17A levels, five nights of sleep restriction are accompanied by increased heart rate; both proinflammatory cytokines and hypertension are important risk factors for development of cardiovascular disease." (PMID 24367384, 2013). "It is speculated that multiple inflammatory factors such as IL-6a, IL1β, and TNF-α play a crucial role in BPH and cardiovascular diseases." (PMID 40636389, 2025). "In addition to the anticipated results in reducing cardiovascular diseases, the CANTOS trial delivered an unexpected finding: the overall mortality rate remained unchanged, despite the inhibition of IL-1β leading to a weakened innate immune system." (PMID 40079000, 2025). "The proinflammatory cytokine Interleukin-1β (IL-1β) participates in the vascular inflammatory and oxidative responses and influences vascular smooth muscle cells (VSMC) phenotype and function, as well as vascular remodelling in cardiovascular diseases." (PMID 36937865, 2023). "Tie-2 and IL-1β may be important mediators between inflammation and vascular dysfunction in patients with SCZ and may also be one of the predictors of increased cardiovascular disease in this population." (PMID 37491201, 2023). "By analyzing the effect of IL-1β gene knockout on apoptosis and expression of other cytokines of smooth muscle cells interfered by CSE, we can find new targets for preventing the harm of smoking to cardiovascular diseases." (PMID 36791122, 2023). "The IL-1β blockade of canakinumab, which is not an application for AD, reduced vascular inflammation in patients with cardiovascular disease and reduced recurrent cardiovascular events." (PMID 36362231, 2022). "Previous studies have confirmed that vascular endothelial inflammatory factors IL-1β, TNF-α, and adhesion factors ICAM-1 and VCAM-1 are essential markers of vascular endothelial injury and dysfunction, which can predict cardiovascular disease, and correlate with the severity of ACS." (PMID 35302437, 2022). "In cardiovascular diseases, the anti-inflammatory effects of resveratrol include inhibition of intracellular adhesion molecule 1 (ICAM-1), and induction of nitric oxide synthase (iNOS) and IL-1β mRNA expression in coronary arterial endothelial cells." (PMID 34287272, 2021).
cardiovascular disease (continued). "Among uninfected ambulatory adults without cardiovascular disease, RDW was associated with elevated pro-inflammatory cytokines (TNF-α, IL8, IL6, IL1b), but not regulatory cytokines (TGFb)." (PMID 33089037, 2020). "Additionally, LncRNA RP5-833A20.1 has also been reported to elevate the levels of inflammatory factors, such as IL-1β, IL-6, and, TNF-α in THP-1 macrophages in cardiovascular disease." (PMID 32629426, 2020). "IL-1β, TNF-α, and IL-6 stimulated the liver to produce high-sensitivity CRP (hs-CRP), which had a strong relationship with the recurrent events of cardiovascular diseases as shown in several randomized clinical trials." (PMID 29403392, 2018). "Our study provided the evidence that IL-1β involves in CSE-induced PAPP-A expression and apoptosis in vascular smooth muscle cells, which might be considered as a potential clinical target for preventing of cigarette smoking-induced cardiovascular diseases." (PMID 36791122, 2023). "Thus, IL-1β blockade failed to increase the overall survival rate of the patients but acted as a proof of concept for the approach of targeting the immune system in addition to typical cholesterol management to reduce adverse cardiovascular disease outcomes." (PMID 33374145, 2020). "On the basis of the probable involvement of IL-1β expression in migration and proliferation of SMCs, our findings suggest an additional mechanism by which EORP treatment may be important in preventing the progression of cardiovascular disorders and inflammation." (PMID 24723958, 2014). "Interestingly, canakinumab (a selective anti-IL-1β monoclonal antibody) decreased neutrophil counts to lower NLR, which in turn decreased adverse endpoint events of cardiovascular disease with no discernible effect from lipid levels, which may indicate that neutrophil played a more vital role." (PMID 38629070, 2024).
neurodegenerative disease (258 papers, 2009 to 2026). A disorder of the central nervous system characterized by gradual and progressive loss of neural tissue and neurologic function. "The plasma levels of pro-inflammatory cytokines (IL-6, TNF and IL-1β) are accepted as risk factors in cardiovascular and neurodegenerative diseases and increase in elderly with various comorbidities." (PMID 40149697, 2025). "During the inflammatory process, HMGB1 is secreted from necrotic cells and binds to many receptors, which triggers the release of many cytokines that cause inflammation and the development of neurodegenerative diseases, including IL-6, TNFα, and IL-1β." (PMID 41351800, 2025). "Previously NLRP3/Caspase1/IL-1β has been implicated in central immune and neurodegenerative diseases." (PMID 37946206, 2023). "Interleukin-1β (IL-1β) is one of the most potent pro-inflammatory cytokines implicated in a wide range of autoinflammatory, autoimmune, infectious, and degenerative diseases." (PMID 37079558, 2023). "Increasing levels of major proinflammatory cytokines, including TNF-α, IL-1β, and IL-6, are associated with several inflammatory-related neurodegenerative diseases." (PMID 37049819, 2023). "Neurodegenerative diseases like AD are associated with increased neuroinflammatory markers (e.g., IL-1β and TNF-α) and loss of synaptic markers (e.g., synaptophysin and drebrin)." (PMID 35742911, 2022). "Crucial in the pathogenesis of neurodegenerative diseases is the process of neuroinflammation that is often linked to the pro-inflammatory cytokines Tumor necrosis factor alpha (TNFα) and Interleukin-1beta (IL-1β)." (PMID 35625761, 2022). "The NLRP3 inflammasome is a crucial signaling node in microglia that ultimately controls the maturation of pro-inflammatory interleukin (IL)-1β and IL-18 and has been linked to a multitude of neurodegenerative diseases." (PMID 31131421, 2019). "TNF-α and IL-1β are typical proinflammatory cytokines associated with degenerative diseases, and they induce inflammatory disease by affecting the synthesis of mediators such as PG, leukotriene, and NO." (PMID 31635294, 2019). "This is critical because overproduction of IL-1β can cause cognitive dysfunction in rodent models and increased IL-1β in aged individuals is associated with risk of neurodegenerative diseases such as Alzheimer’s." (PMID 30154787, 2018). "IL-1β promotes the inflammatory reaction of glial cell and leads to diseases related to neuronal loss, such as ischemic and traumatic brain injury and neurodegenerative disease." (PMID 28937602, 2017). "Elevation of TNFα and IL-1β is a hallmark of neuroinflammation, which is a critical etiology in neurodegenerative diseases." (PMID 28103888, 2017). "IL-1β production has been linked to neuroinflammatory conditions and neurodegenerative diseases for a long time with both beneficial and detrimental effects described." (PMID 26091541, 2015). "Many studies demonstrated that some of the proinflammatory cytokines, such as TNF-α, IL-1β, and IL-6, play a key role in the development and maintenance of inflammation, and this cytokine elevation is associated with neurodegenerative diseases." (PMID 25157358, 2014). "IL-1β was selected based on its well-characterized participation in neuronal injury associated with inflammatory and neurodegenerative diseases of the brain." (PMID 22642771, 2012). "Pro-inflammatory proteins like interleukin 1 beta (IL-1β), IL-6, and TNFα are produced in greater amounts by this activated microglia, which results in prolonged neuroinflammation and important processes linked to neurodegenerative diseases." (PMID 39996037, 2025). "The link between IL-1β and neurodegeneration has been validated through clinical studies showing that patients with neurodegenerative diseases exhibit higher IL-1β levels than healthy controls, which are associated with exacerbated CNS immune reactions and greater disease severity." (PMID 41403939, 2025).
neurodegenerative disease (continued). "Similarly, the link between C9orf72, associated with neurodegenerative diseases and neuronal apoptosis, and IL1B, a pro-inflammatory cytokine, underscores the potential interplay between neurodegeneration and inflammation in PND pathogenesis." (PMID 38481183, 2024). "Pro-inflammatory factors such as TNF-α, IL-6, and IL-1β, released by activated microglia during neuroinflammation, are pivotal in initiating inflammatory responses, regulating cytokine cascades, and being implicated in neurodegenerative diseases." (PMID 39201475, 2024). "Three neurodegenerative diseases are characterized by the abnormal aggregation of proteins in the central nervous system (CNS), i.e., Aβ, α-synuclein, and mHTT, which cause the pathogenesis of IL-1β in and progression of AD, PD, and HD, respectively." (PMID 35219323, 2022). "Activation of astrocytes and microglias result in the production of major proinflammatory cytokines (TNF-α, IL-6, or IL-1β) and neurotoxic factors (reactive oxidative species and tumor necrosis factor-α), which are typically associated with neurodegenerative diseases including AD." (PMID 32587516, 2020). "The expressions of IL-1β, IL-6 and iNOS are associated with neurodegenerative diseases." (PMID 28340576, 2017). "Microglia activated by LPS stimulation led to the production of proinflammatory cytokines and mediators, such as TNF-α, IL-6, and IL-1β, and their chronic increase predisposes the CNS to neuroinflammation, which may result in the development of neurodegenerative diseases, such as AD." (PMID 40720378, 2025). "Under conditions of neurodegenerative diseases, ROS activates the transcription factor NFκB in glial cells, causing it to transfer from the cytoplasm to the nucleus, thereby promoting the transcription of some important pro-inflammatory genes, including IL-1β, IL-6, and TNF-α." (PMID 40699625, 2025). "IL-1β is associated with impaired neurogenesis and hippocampal dependent memory 103–105, has been correlated with Aβ accumulation and neurofibrillary tangles (NFTs) 106 and can result in the aberrant release of glutamate that results in neuronal death in many neurodegenerative disease." (PMID 41497643, 2025). "The robust NLRP3 inflammasome response, upregulation of NLRP3 and IL-1β following LPS + ATP/NG stimulation, highlights their relevance for studies of inflammasome-targeting drugs in neurodegenerative diseases." (PMID 41596340, 2026). "Together, these findings highlight the therapeutic potential of macrophage-targeted PEGylated liposomes in controlling IL-1β-mediated neuroinflammation in MS and potentially other neurodegenerative diseases." (PMID 41624869, 2026). "The consequences of AIM2 activation can provide a protective effect that goes beyond canonical ASC speck formation and IL-1β secretion, highlighting diversity in inflammasome functions in neurodegenerative diseases." (PMID 41386298, 2025). "NMN has been shown to mitigate these effects by modulating oxidative stress markers (e.g., SOD, CAT) and inflammatory cytokines (e.g., TNF-α, IL-1β, IL-6), thus underscoring its potential in protecting against neurodegenerative diseases." (PMID 40276601, 2025). "Alcohol-associated neurodegenerative diseases have been linked to increased apoptosis, excitotoxicity, lipid peroxidation, and elevated DAMP secretion such as IL1β, ROS, mtDNA, and HMGB1." (PMID 40216765, 2025). "Pro-inflammatory cytokines, including tumor necrosis factor-alpha (TNF-α), interleukin-1beta (IL-1β), IL-6, and IL-8, have been observed to exacerbate neuronal damage and contribute to the progression of neurodegenerative diseases." (PMID 40309866, 2025). "The NLRP3 inflammasome is a multiprotein complex that plays an important role in several neurodegenerative diseases, being essential for cleavage and subsequent release of IL1b from activated microglia." (PMID 41562096, 2025).